STAT3 (signal transducer and activator of transcription 3)
Diseases named in the same sentence as STAT3 in open-access papers (continued):
Sharing a sentence is not in itself a finding about the gene and the disease.
colitis (continued). "Here, we report the role of STAT3 activation in type I collagen-expressing fibroblasts during the growth of colitis-associated CRC, providing evidence for a functional contribution of this CAF subset during tumor development." (PMID 35326623, 2022). "We demonstrate that the reduction in STAT3 activity significantly increased susceptibility to DSS-induced colitis, which was manifested by severe weight loss, increased inflammation, and decreased intestinal barrier function." (PMID 33673239, 2021). "Compared to wild-type mice, which only developed mild colitis, a reduction in STAT3 activity resulted in significant weight loss in GP130∆STAT/+ and dox-treated shStat3 mice after DSS treatment." (PMID 33673239, 2021). "CAMK2γ in intestinal epithelial cells modulates colitis-associated colorectal carcinogenesis by enhancing STAT3 activation." (PMID 33761465, 2021). "The GP130∆STAT/+ and shStat3 mouse models recapitulated previous studies where IEC-specific Stat3 ablation resulted in enhanced susceptibility to colitis with increased weight loss, histological injury, and inflammation in response to DSS." (PMID 33673239, 2021). "In colitis, while STAT3 activation leads to pathogenic T cell survival in the adaptive compartment, it contributes to the suppression of inflammation in colonic epithelial cells and macrophages." (PMID 34571853, 2021). "It suppresses colitis symptoms by inhibiting the IL-6/STAT3 signaling pathway in IL-10 deficient mice as well as in an in vitro culture of colonic explants of patients with CD." (PMID 34068714, 2021). "Defects in IL-10RB are described to cause severe colitis, as several anti-inflammatory processes are regulated by IL-10 binding to the IL-10R and subsequent STAT3 phosphorylation and activation." (PMID 33804706, 2021). "In accordance with the fact that expression of c-Maf (and RORγt) in Treg cells is dependent on STAT3 activation, uncontrolled intestinal Th17 cell responses and spontaneous colitis were also detected in Treg cell-specific STAT3-deficient mice." (PMID 33193456, 2020). "This possibility is supported by the known ability of Stat and Runx proteins to physically interact with each other, and the spontaneous colitis induced in mice harboring Stat3-deficient MNP." (PMID 32453801, 2020). "The subsequent comprehensive in silico analysis revealed the ability of TM to bind to the active sites of key colitis-associated regulators, including Akt1, Src, STAT3 and dopamine receptor D2." (PMID 32455822, 2020). "Simultaneously, the level of activated STAT3 increases together with the continuum of dysplasia to colitis-associated cancer." (PMID 32863742, 2020). "Recent study has shown that TRIM27-activated STAT3 to promote colitis and colitis-associated carcinogenesis." (PMID 31921311, 2019). "Loxl3 deficiency leads to constitutive STAT3 K685 acetylation causing reduced Th17 differentiation associated with resistance to DSS-induced colitis in mice." (PMID 31480382, 2019). "Type III Reg protein linked to STAT3-associated cytokine stimulation plays a pivotal role in the pathophysiology of DSS-induced colitis in mice." (PMID 31780871, 2019). "The link between type III Reg and STAT3-associated cytokines appears to play a pivotal role in the pathophysiology of DSS-induced colitis." (PMID 31780871, 2019). "Taken together, our study demonstrated that silibinin administration ameliorated colitis and inhibited colitis-associated tumorigenesis via inhibition of IL-6/STAT3 signaling pathway." (PMID 30498394, 2018). "A recent study has reported that SPHK1 leads to the constitutive activation of STAT3 in colitis-associated CRC." (PMID 30555277, 2018). "During experimental colitis, the ablation of IL-22/STAT3 signaling using tyrosine kinase 2 (TIK2) deficient mice exacerbates inflammatory bowel disease." (PMID 30235866, 2018).
colitis (continued). "Deficiency of TRIM27 significantly impairs dextran sulfate sodium (DSS)-induced STAT3 activation, inflammatory cytokine expression and colitis as well as azoxymethane (AOM)/DSS-induced colitis-associated cancer in mice." (PMID 30143645, 2018). "SPHK1 is upregulated in CRC cancer patients and leads to constituent activation of STAT3 in colitis-associated CRC." (PMID 30555277, 2018). "Overexpression of IL-22 in the colon of mice with a local gene delivery led to attenuated colitis associated with STAT3 activation and increased production of mucus-associated proteins by epithelial cells." (PMID 29967613, 2018). "Genetic deletion of STAT3 in myeloid cells (neutrophils and macrophages) and enterocytes resulted in chronic colitis, suggesting that STAT3 activation in these two cell types, associated with innate immunity, were protective against colitis." (PMID 30081609, 2018). "In a recent study, adiponectin-deficient mice treated with DSS exhibited more severe colitis accompanied by an increased presence of activated B cells, pro-inflammatory cytokines such as IL-1β, IL-4, and IL-6 and increased STAT3 signaling in the colon." (PMID 30369924, 2018). "The anti-inflammatory effect of STAT3 also corroborates with mice studies observing that mice having STAT3-deficient macrophages produce excessive cytokine and develop colitis." (PMID 28871257, 2017). "The ETBF causes colitis, colonic hyperplasia and tumor initiation in Min mice by signal transducer and activator of transcription 3 (STAT3) and a pro-inflammatory Th17 response." (PMID 29213996, 2017). "The enterotoxigenic Bacteroides fragilis can cause colitis, colonic hyperplasia, and tumor formation by activating STAT3- and TH17-dependent pathways." (PMID 29228570, 2017). "Recent studies have demonstrated that the IL-6/STAT3 pathway is a crucial tumor promoter in colitis-associated cancer." (PMID 28852270, 2017). "A link between S1P and STAT3 signaling is exemplified by studies showing that S1P enhances colitis associated cancer via a malicious amplification loop involving SK1, S1P1, NF-κB, STAT3 and IL-6." (PMID 28241498, 2017). "Macrophage-specific conditional deletion of at least two IBD susceptibility loci, Il10ra and Stat3 knockout has been shown to generate spontaneous colitis in mice." (PMID 28263993, 2017). "SAMe and MTA inhibited IL-6/STAT3 signaling and lowered tumor burden in a colitis-associated cancer model." (PMID 29108270, 2017). "In the present study, we investigated the possible protective effects of Perilla frutescens extract (PE) against DSS-induced colitis and underlying molecular mechanisms, with special focus on the inflammatory signal transduction mediated by NF-κB and STAT3." (PMID 28848431, 2017). "Later, another mechanism of STAT3-mediated pathogenic contribution was detected as STAT3 was found to be essential for the differentiation of Th17 cells and Th17-dependent murine colitis." (PMID 26938566, 2016). "Our previous study reported that oroxylin A, a natural flavonoid, inhibited colitis-associated carcinogenesis through modulating IL-6/STAT3 pathway in AOM/DSS mouse model and in HCT116 cells." (PMID 27057094, 2016). "Colitis-associated phospho-nuclear factor κB (NF-κB) p65, and -STAT3, which were detected readily in WT mice, were barely detectable in Lrrc19 KO mice." (PMID 26776522, 2016). "Excess activation of STAT3 in enterocytes promotes, whereas ablation of STAT3 reduces tumor cell proliferation through G1 and G2/M cell cycle progression in mouse models of colitis-associated CRC." (PMID 26871465, 2016). "The enterotoxigenic Bacteroides fragilis causes colitis, colonic hyperplasia, and tumor formation through activation of Stat3- and TH17-dependent pathways." (PMID 27863401, 2016). "This perception is also based on the observation that inactivation of STAT3 in neutrophils and macrophages causes chronic murine colitis via increased Th1 responses and decreased signal transmission of IL-10." (PMID 26938566, 2016).
colitis (continued). "In this study, Grim19 inhibited DSS induced colitis progression and weight loss in mice by downregulating the production of STAT3 and proinflammatory cytokines, including TNF-α and IL-6, in colonic inflammation." (PMID 27258062, 2016). "Conversely, mice with a conditional deletion of SHP-2 in IECs developed colitis-associated adenocarcinomas with age, associated with sustained activation of Wnt/β-catenin, NFκB and STAT3 signalings in the colonic mucosae." (PMID 27582544, 2016). "This was related to CAC by the observation that STAT3 hyperactivation in IECs not only led to decreased susceptibility for colitis but also to increased occurrence and growth of tumors through IL-6 and IL-11." (PMID 26938566, 2016). "Based on these findings, we strongly believed that controlling STAT3 expression during UC is a novel approach for avoiding the development of colitis-associated cancer." (PMID 26075036, 2015). "Induction of pro-inflammatory cytokines and pro-inflammatory mediators such as COX2 and STAT3 in colon tissue have been demonstrated in animal models of colitis and colitis associated cancer (CAC)." (PMID 25460165, 2014). "The activation of STAT3, which plays an important role in the inflammatory response, in intestinal epithelial cells and myeloid cells promotes the development of colitis-associated cancer and influences the anti-inflammatory effects of IL-10." (PMID 25286337, 2014). "In particular, animal studies have revealed the crucial role of an intact Stat3 in intestinal homeostasis and its protective role as IEC-specific Stat3-deficient mice are highly susceptible to chemically induced colitis." (PMID 25593900, 2014). "Knocking out STAT3 in colon epithelial cells led to reduced tumor formation in a model of colitis-associated CRC in mice." (PMID 23940556, 2013). "A recent study demonstrated that intestinal epithelial cell-specific STAT3 deficiency results in altered STAT3 activation in the immune cells and the expansion of IL-17A-secreting intestinal T cells in a colitis model." (PMID 23950992, 2013). "Recently, we have found that STAT3-deficient T cells fail to mount either systemic or intestinal inflammation in T cell transfer colitis." (PMID 20732640, 2010). "Additionally, genetic ablation of PRMT1 in myeloid cells not only impairs STAT3 activation but also exacerbates colitis and promotes inflammation-associated tumorigenesis." (PMID 42220092, 2026). "This is mainly because miR-148a directly targets upstream regulators of NF-κB and STAT3 signaling, leading to the activation of NF-κB and STAT3 in macrophages and connective tissues, which affects the pathogenesis of colitis and colitis-associated tumor formation." (PMID 38903520, 2024). "In addition, STAT3 knockout ameliorated various histological changes caused by the high-LCFA diet in colitis." (PMID 38233383, 2024). "In addition, the sphingosine-1-phosphate inhibitor FTY720 reduces colitis-associated colorectal tumour growth via indirect downregulation of STAT3 and activation of NF-κβ signalling." (PMID 38600086, 2024). "First, the IL-6/STAT3 pathway is a key signaling pathway in colitis-associated colorectal cancer." (PMID 37251321, 2023). "Additionally, a non-toxic dose of DON has been found to exacerbate DSS-induced colitis through the JAK2/STAT3 signaling pathway, suggesting its association with IBD risk." (PMID 37368693, 2023). "Our findings indicated that the expression of CD73 on ERCs could improve intestinal barrier function and modulate the immune response in the murine colitis model, and the process is associated with STAT3-mediated DCs." (PMID 37180168, 2023). "In addition, the IL‐6 downstream STAT3 signalling pathways are persistently activated during colitis‐associated carcinogenesis." (PMID 35363937, 2022). "Stat3 activation has also been associated with ETBF-related colitis and tumour development." (PMID 35468857, 2022).
colitis (continued). "Meanwhile, studies in mice demonstrated that STAT3 prevents apoptosis of infiltrating pathogenic T cells, resulting in chronic intestinal inflammation, which indicated that STAT3 activation in T cells contributes to colitis." (PMID 36498596, 2022). "On the basis of our results, strategies blocking STAT3 activation in defined CAF populations of colitis-associated CRC could be promising." (PMID 35326623, 2022). "Genetic deletion of STAT3 in enterocytes rendered mice more susceptible to experimental colitis." (PMID 36498596, 2022). "Here, we show that mice with reduced STAT3 activity are highly susceptible to DSS-induced colitis." (PMID 33673239, 2021). "Moreover, PDCD4 deficiency in mouse models aggravates colitis and colitis-associated CRC by promoting the IL-6/STAT3 pathway." (PMID 34771727, 2021). "Furthermore, downregulation of SOCS3 was also observed in patients where colitis resulted in carcinogenesis, suggesting that loss of inhibition on STAT3 promotes the development of cancer during colitis." (PMID 34604264, 2021). "In addition, aberrant STAT3 activation is associated with malignant transformation and pathogenesis of the majority of solid cancers, including colitis-associated CRC and gastric cancer." (PMID 33673239, 2021). "Previous studies have demonstrated that G-CSF could promote MDSCs’ survival and activation through the STAT3 signaling pathway in a mouse colitis-associated cancer model." (PMID 33384962, 2020). "The increased tumorigenesis found in these mice at the end of the CAC model along with the results obtained with Stat3ΔIEC; Stat6−/− mice support the concept that tumor formation and growth in Stat6-deficient mice is promoted by Stat3 activation in enterocytes at the earlier DSS-induced colitis." (PMID 30353167, 2019). "Furthermore, we showed that the in vivo expression of Reg IIIβ/γ was significantly correlated with that of STAT3-associated cytokines in this model of DSS-induced colitis." (PMID 31780871, 2019). "However, STAT3 mediates the activation of acquired immune responses, which seem to play a role in the pathogenesis of colitis by promoting the survival of pathogenic T cells." (PMID 31277507, 2019). "It has been shown that STAT3 is activated in intestinal epithelial cells following C. rodentium infection in vivo and that mice conditionally deficient in STAT3 in epithelial cells (Stat3ΔIEC) were highly susceptible to infection and developed severe colitis after infection with C. rodentium." (PMID 30818341, 2019). "Similarly, STAT3-mediated activation of acquired immune responses plays a pathogenic role in colitis by enhancing T cells survival." (PMID 30545135, 2018). "However, YAP also increased colitis-associated carcinoma susceptibility, which is similar to the effect from STAT3 activation." (PMID 29396428, 2018). "In conclusion, silibinin could protect against colitis-associated tumorigenesis in mice via inhibiting IL-6/STAT3, which showed promising chemopreventive potential of CAC." (PMID 30498394, 2018). "In line with this evidence, increased inflammation and IEC death in a three times DSS-mediated colitis of IL-6-deficient mice is a result of impaired IL-6-mediated signal transducer and activator of transcription 3 (Stat3) action providing survival capacities in normal and premalignant IECs25." (PMID 29695802, 2018). "In addition, a link between TGF-β signaling and IL-6/STAT3 signaling in the tumorigenesis of colitis-associated CRC has been demonstrated." (PMID 28852270, 2017). "In addition, ApoA-I inhibited STAT3, which plays a major role in suppressing LPS-induced production of the inflammatory cytokine IL-6, in a mouse model of colitis-associated carcinogenesis." (PMID 29245934, 2017). "Moreover, DSS induced colitis progression in a Grim19 transgenic mouse line was inhibited in association with a reduction in STAT3 and IL-17 expression." (PMID 27258062, 2016).
colitis (continued). "Similarly, growth hormone caused a downregulation of STAT3 signaling which led to less severe murine colitis going along with increased LPMC apoptosis." (PMID 26938566, 2016). "Consequently, systemic downregulation of STAT3 in MDSCs withholds the risk of inducing immune-related adverse events such as colitis." (PMID 27029037, 2016). "Our data indicate that this gp130/STAT3-mediatedimmunoprotection in DSS-induced colitis is independent of the previously reportedbeneficial effects of STAT3 activation on intestinal epithelial cells in animalmodels of colitis-associated tumorigenesis." (PMID 26848037, 2016). "Furthermore, higher expression of phosphorylated STAT3 was associated with the disease activity in animal models of colitis as well as in IBD patients." (PMID 24451125, 2013). "Thus KLF5 and STAT3 signaling provide important areas for further study in colitis and represent potential diagnostic and therapeutic targets for IBD and other diseases characterized by injury and disruption of intestinal epithelia." (PMID 22675454, 2012). "IL6 signaling is mediated by STAT3 that is also associated with colitis disease development." (PMID 20423518, 2010). "Thus, STAT3 deficiency aggravates DSS-induced colitis in mice." (PMID 39773987, 2025). "Furthermore, flavonoids and polysaccharides from okra flowers have been shown to possess the ability to attenuate induced colitis‐associated cancer through the regulation of NFκB/IL‐6/Stat3, JAK2/Stat3, MAPKs, PI3K/AKT, and Wnt/β‐catenin signal transductions in mice model." (PMID 38726403, 2024). "Furthermore, TRIM27 promotes IL-6-induced STAT3 activation by mediating ubiquitination of protein inhibitor of activated STAT3, thereby aggravating psoriasis (a chronic inflammatory disease that predominantly affects the skin and joints), colitis, and colitis-associated cancer." (PMID 34177938, 2021). "Previous study has shown that inhibiting or blocking the activation of IL-6/STAT3 signaling pathway can attenuate the colon injury and inflammation in DSS-induced colitis, and RNA-seq analysis also pointed out that the underlying mechanism may related with IL-6/STAT3 pathway." (PMID 32517784, 2020). "Indeed, it was shown in the same study that deletion of STAT3 in the intestinal epithelium led to more severe DSS colitis with pronounced colonic ulcerations and body weight loss, indicating that the IL-6 response in the intestinal epithelial cells was important for regeneration." (PMID 31694340, 2019). "Moreover, recent findings demonstrated that cocoa suppresses the development of colitis-associated tumorigenesis by modulating NF-kB/IL-6/Signal transducer and activator of transcription 3 (STAT3) signaling pathways and also induces apoptosis by activating caspase-3 in a mouse model." (PMID 31031748, 2019). "Moreover, selective deletion of STAT3 in macrophages causes spontaneous colitis in mice." (PMID 29725003, 2018). "Importantly, colitis-associated tumors developed in Sdc1-defficient mice were characterized by increased local production of IL-6, activation of STAT3, as well as induction of several STAT3 target genes that act as important effectors of colonic tumorigenesis." (PMID 28350804, 2017). "Based on ourfindings we therefore hypothesized that the altered colitis susceptibility ofgp130757F/F mice may be due to STAT3 activation in myeloidcells, and determined the expression of IL-19 and IL-33 in peritonealmacrophages of WT and gp130757F/F mice with and without LPSstimulation." (PMID 26848037, 2016). "Interestingly, STAT3 activation in enterocytes may also increase the development of colitis-associated cancer; thus the long-term effects of KLF5-mediated STAT3 induction in colitis merit further study." (PMID 22675454, 2012).